RNU6-1324P (RNA, U6 small nuclear 1324, pseudogene)
Gene: Small nuclear RNA gene on chromosome 8 (66,501,205 to 66,501,311, reverse strand). Ensembl gene ENSG00000206949.
Homologues: Orthologues: chimpanzee U6 (99% identical), macaque U6 (94% identical), rabbit U6 (84% identical), rat U6 (84% identical). Paralogues in human: RNU6-1060P (87% identical), RNU6-116P (87% identical), RNU6-338P (87% identical), RNU6-1011P (86% identical), RNU6-1075P (86% identical), RNU6-1124P (86% identical), RNU6-12P (86% identical), RNU6-13P (86% identical), RNU6-166P (86% identical), RNU6-32P (86% identical), RNU6-33P (86% identical), RNU6-41P (86% identical), and 1288 more.